CD274 (CD274 molecule)
Diseases named in the same sentence as CD274 in open-access papers (continued):
Sharing a sentence is not in itself a finding about the gene and the disease.
tumor (continued). "Since CLDN7, CLDN11 and CD274 correlate with the invasive and metastatic ability of tumours, we further did Wound healing assays and transwell assays." (PMID 38575994, 2024). "We found that CD274 was mainly expressed in tumor cells, whereas the expression of PDCD1 in the immune cells in the low-DR group was higher than that of those in the high-DR group." (PMID 38507875, 2024). "CD274 (CD274 molecule), also named PDL1, encodes an immune inhibitory receptor ligand which was involved in the immune escape process for tumor." (PMID 38347589, 2024). "Programmed cell death protein 1 (PDCD1, PD-1, CD279) and programmed cell death ligand 1 (PD-L1, CD274/B7-H1) are regarded as key targets for anti-tumor immunotherapy currently." (PMID 39076970, 2024). "To investigate the correlation between AMG510 resistance molecules and CD274 (PDL1) in tumor immune escape, we analyzed their co-expression patterns within these clusters." (PMID 38338834, 2024). "After the t-test, we confirmed that significant differences existed in the expression of CD274 between tumor and normal tissues in these cancers." (PMID 38166842, 2024). "CD274 (PD-L1) is an immune checkpoint molecule that inhibits the host’s immune response against tumor cells and regulates inflammation development." (PMID 38440722, 2024). "CD274 expression profoundly influences cancer aggressiveness, clinical outcomes, tumour development, and prognosis, establishing itself as an independent adverse prognostic indicator for ccRCC." (PMID 38802631, 2024). "One important predictive biomarker, known as PD-L1, CD274, or B7–H1, is a transmembrane protein that is frequently expressed on tumour cells." (PMID 39000359, 2024). "The upregulated genes in PTCL‐TBX21 included Th1‐related genes, including CXCR3, CD38, INFG, CXCL9, CXCL11, IL27, and genes associated with tumor immunity, such as CD274 (PD‐L1), LAG3, and IDO1." (PMID 38234210, 2024). "The association between pretreatment tumor inflammation and the efficacy of BEMPEG + NIVO versus NIVO was evaluated using a four-gene signature, comprised of the following genes: CD274 (PD-L1), CD8A, LAG3, and STAT117 (see “Methods”)." (PMID 39025948, 2024). "CD274 antigen, also called programmed death ligand 1 (PD-L1), is crucial for the escape of tumor cells from immunosurveillance." (PMID 38674080, 2024). "The overexpression of DDX3X resulted in the upregulation of CD274 mRNA expression and consequently increased PD-L1 expression, which is known to facilitate immune evasion by various tumor cells." (PMID 38316768, 2024). "In 13 forms of cancer, significant changes in CD274 expression were found between tumor and normal tissue." (PMID 38166842, 2024). "In light of these findings, it is evident that miR-4429 serves to suppress tumour growth in ccRCC by inhibiting the activation of the PI3K/AKT signalling pathway through targeting CD274." (PMID 38802631, 2024). "Immune checkpoint blockade (ICB) has also shown significant efficacy in patients with high expression of PDL1 (CD274), tumor mutation burden (TMB), and gene expression profile (GEP) score." (PMID 39449814, 2024). "Studies have found that IFNG, CXCL9, and CD274 expression in tumor specimens correlate to stronger immunotherapy responses." (PMID 38265267, 2024). "The release of HMGB1 can further trigger the expression of CD274 (PD-L1) in tumor cells and inhibit T cell immune function." (PMID 39314628, 2024). "Further studies are needed to elucidate the function of YTHDF and CD274 in the tumor microenvironment and the m6A‐mediated control of transcripts and proteins." (PMID 38351531, 2024). "In tumor cells, we also found that high baseline expression of specific genes, including PCNA, FGF11, FGF18, CD274 (PD-L1) and HLA-A, was associated with a favorable response." (PMID 38245530, 2024). "Overexpression of CD274 in certain cancers contributes to tumor progression and helps evade immune surveillance." (PMID 38610001, 2024).
tumor (continued). "Programmed death-ligand 1 (PD-L1), is a 40 kDa transmembrane protein encoded by CD274 gene, representing a crucial suppressor of anti-tumor immunity." (PMID 38310272, 2024). "DDIR positivity was associated with a pretreatment inflamed tumour microenvironment (TME) and increased expression of biomarkers associated with ICI response such as CD274 (programmed death-ligand 1, PD-L1) and a microsatellite instability RNA signature." (PMID 38744099, 2024). "Programmed cell death ligand 1(PD-L1/CD274), expressed by tumor cells and antigen presenting cells (APCs), is the ligand for Programmed Cell Death 1(PD-1/CD279), on T cells." (PMID 38516270, 2024). "Whole-transcriptome RNA analysis found that the cold nodule demonstrated lower expression of genes related to antigen presentation (HLA) and, paradoxically, classical tumor immune tolerance markers such as PD-L1 (CD274) and CTLA-4." (PMID 38253539, 2024). "The immune checkpoint ligand CD274 (programmed death-ligand 1, B7-H1) inhibits anti-tumor immunity by interacting with the PDCD1 (programmed cell death 1, PD-1) receptor on T lymphocytes in various tumors." (PMID 39119088, 2024). "Pearson analysis also revealed a significant positive correlation relationship between TWIST1 and CD274 mRNA expression levels in individual tumor samples of this dataset (central and right panels)." (PMID 38893094, 2024). "PECAM1 expression was also closely associated with ETS1/PLAT and CD274 (PDL1)/IFNGR1, indicating close involvement of tumor angiogenesis with unique proteolysis and tumor immunity." (PMID 38557819, 2024). "Because MYC can regulate the immune response by promoting CD274 transcription in tumor cells, we investigated this possibility in the mouse models." (PMID 36928817, 2023). "Gas plasma treatment reduced the expression of immune-inhibitory CD152 and CD274 but also ICD-related calreticulin (CRT) in WT tumours." (PMID 37460712, 2023). "Tumor cells often express PD-1 ligand-1 (PD-L1), also known as B7 homolog 1 (B7-H1) or CD274, a type 1 transmembrane protein that leads to the inhibition of PD-1–positive T lymphocyte proliferation, cytokine production, and cytolytic activity." (PMID 38038129, 2023). "All immune checkpoints were significantly different between the normal and tumor groups (P < 0.05), in which PDCD1, CTLA4, and HAVCR2 were highly expressed in tumor tissues, while CD274, LAG3, and PDCD1LG2 were highly expressed in normal tissues." (PMID 37872211, 2023). "Recurrent HCC tumor cells interact with cDC2/LAMP3+ DCs via CD274/CD80 and CTLA4/CD80, leading to the formation of clusters around DCs and subsequently reducing antigen presentation and T cell activation efficiency." (PMID 38012715, 2023). "The bona fide candidate genes CD8A, CD4, and CD274 showed increased expression in T cells and tumor cells, respectively." (PMID 36672341, 2023). "Our study revealed several key genes with high degrees involved in the subnetwork, including CD274, CD20, and FASLG that have been widely used in clinical tumor treatment, and they were positively associated with poor prognosis in CRC." (PMID 36660243, 2023). "PD-L1 (also known as CD274 or B7H1) is expressed on tumor cells and is of great importance for tumor immune escape and for the development of an immune microenvironment permissive for neoplastic growth." (PMID 37026608, 2023). "With RNA‐sequencing, IL‐1β enhanced a range of immune inhibitory molecules expression on tumor cells, including CD274, PDCD1LG2, and IDO1." (PMID 37009412, 2023). "Kataoka’s study showed that rare structural variants in the UTR region (including 5' UTR and 3' UTR) of CD274 (Protein name: PD-L1) gene could increase the expression level of PD-L1 protein in a variety of tumors, which might induce the development of immune escape behavior in tumor cells." (PMID 36717553, 2023). "The PD1 (PDCD1)-PD-L1 (CD274) receptor-ligand pairs were identified between PD1 + T cells and PD-L1 + tumor cells." (PMID 36944944, 2023).
tumor (continued). "At the early stage of YUMM3.3 tumor growth examined here, Activin-A secretion increased the expression of the ligands Lgals3, Hmgb1, Lgals9, CD274 in various cell types." (PMID 38304252, 2023). "With cSMART 2.0 technology, we obtained 100% concordance between blood-based ctDNA and tumor tissue-based gDNA for CD274 structural variation detection." (PMID 36717553, 2023). "Current research indicated that CD274 (PD-L1) is expressed on the surface of tumor cells and it can interact with PD-1 which has the potential to reduce the anti-tumor effect." (PMID 36676763, 2023). "The downregulation of Mrc1 (CD206) and Cd274 (PD-L1) was validated analyzing their protein expression on tumor-infiltrating live cells following Adoi treatment." (PMID 37553182, 2023). "Comparing tumor with non-tumor samples, we found an increase in CD274 expression on classical, intermediate, and, in a lower extension, non-classical monocytes." (PMID 37370832, 2023). "A recent study suggested that the co-inhibition of LGALS9 and CD274 (PDL-1) resulted with a more effective tumor growth inhibition in PDAC19." (PMID 37945567, 2023). "The immunomodulatory role of CD274 in tumours was demonstrated by Honjo’s group, winner of the Nobel Prize in 200249." (PMID 37225853, 2023). "By consensus clustering, two independent clusters with obvious tumor heterogeneity, distinct CD274 expression, and a diverse TME landscape were established." (PMID 37629061, 2023). "A survey of immune checkpoint receptor ligands revealed upregulation of Lgals3 in fibroblasts, Hmgb1 in tumor cells, and Lgals9 and Cd274 across cell clusters." (PMID 38304252, 2023). "This indicated that there was an abnormal expression profile of CD274 expression levels in the tumor samples." (PMID 36959799, 2023). "Our integrative data set allowed us to examine the relationship between tumor CD274 expression and the tissue abundance of F. nucleatum while adjusting for selection bias and potential confounders." (PMID 37538192, 2023). "Increased CD274 mRNA expression (encodes PD-L1) has been reported to be a significant predictor of better RFS, mainly in pT1 tumours." (PMID 36928373, 2023). "HIF-1α during hypoxia induces the PDL-1 (CD274) expression in tumor cells, DCs, TAMs, and MDSCs to support immunosuppressive TIME." (PMID 37275901, 2023). "We validated our finding using 24 paired normal and tumor tissue samples and found significantly elevated CD274 mRNA expression in the tumor tissues compared to the corresponding normal tissues; this pattern was also observed for CYSLTR1 mRNA expression." (PMID 37316937, 2023). "It interacts with its ligand, PD‐L1 (also called CD274 or B7‐H1), in tumor cells or other antigen‐presenting cells (APCs)." (PMID 36567273, 2023). "To compare the PD-L1 transcript (CD274) level between normal and tumor tissues in patients with CC, we employed the TCGA-COAD cohort (n = 327) and found higher expression of CD274 in tumor tissues than in normal tissues." (PMID 37316937, 2023). "In a 4T1 tumor treated with cyclophosphamide, the single cell expression of Cd274 was found to increase both in myeloid- and lymphoid-infiltrated cells, independently of its receptor Pdcd1." (PMID 38201582, 2023). "Our results showed that tumor targeting-related immune checkpoint genes such as CD274 (p = 0.0137), TGFB1 (p = 0.0175), PDCD1 (p < 0.001), CTLA4 (p < 0.001), and LAG3 (p < 0.001) were significantly associated with APOC1." (PMID 36969562, 2023). "Based on the expression levels of FRGs, we clustered two subtypes with apparent tumor heterogeneity, and different TME, and CD274 expression levels, which improves the risk stratification and precision therapy for LGG patients." (PMID 37629061, 2023). "In such tumour type, interaction score for the CTLA4‐CD80/86 and PD1‐PDL1 (CD274) is higher in tumour samples compared with normal counterpart." (PMID 36625080, 2023).
tumor (continued). "Overexpression of PD-L1 (CD274), the ligand of PD-1, has been proven to promote immune evasion and tumor growth through enhancing T cell apoptosis in many types of cancer." (PMID 38268926, 2023). "These single cell transcriptome analyses confirmed the induction of CD274 overexpression by cyclophophamide in the 4T1 tumor immune microenvironment, especially in B cells, in Monocyte/Macrophage Lyz2+ or Skfn4+ and in dendritic cells of Slamf7+." (PMID 38201582, 2023). "Across tumors from both stages with available IHC data (n = 295), PD-L1 TPS and CD274 expression in tumor cells were highly correlated (P < 2.2e-16, ⍴ = 0.74)." (PMID 35881197, 2023). "Among them, PDCD1 (PD-1) and CD274 (PD-L1), which play critical roles in tumor immunosuppression and immune therapy, were obviously positively correlated with the risk score." (PMID 37891828, 2023). "mAbs blocking the PDCD1/CD274 checkpoints inhibit the co-inhibitory signal on Teff cells and promote cytotoxic activity against tumor cells." (PMID 37215135, 2023). "Programmed death ligand-1 [PD-L1], also known as CD274, is an immunological checkpoint that aids in anti-tumour immune system suppression." (PMID 36942175, 2023). "Here, we comprehensively analyzed the expression profiles, prognosis, correlations with CD274, and the roles in the tumor microenvironment (TME) of FRGs in LGG." (PMID 37629061, 2023). "A predictive role of tumor CD274 overexpression in specific cancer patients needs further investigations." (PMID 37538192, 2023). "The programmed cell death protein PD-1 (CD279) and its ligand PD-L1 (CD274) form an immune checkpoint, regulating the immune response within the tumor microenvironment." (PMID 37894769, 2023). "PD-L1(PDCD1), CTLA4 and PD1 (CD274) are important immune checkpoints which are in charge of tumor immune escape.Taken the potential carcinogenic function of HHIP in CRC into consideration, the correlation of HHIP with PD-L1, CTLA4 and PD1 was assessed." (PMID 37568084, 2023). "With respect to the gene expression profile, CCL21 increased the expression of tumor-supportive genes such as Vegfa, Mrc1, Arg1, and Cd274 (PD-L1) in microglia, as well as in BMDMs that also showed increased expression of Il-10 and Tgfβ1." (PMID 37314567, 2023). "We found that when co-cultured with CD4+ T cells from tumors in Cd4;Tcf7+/+ mice, 7940b cells expressed more Cd274 compared with tumor cells cultured alone." (PMID 36239683, 2023). "In contrast, CD274/PD-L1 induces glycolysis in tumor cells, depleting glucose from the TME, which is essential for CAR T cell activity." (PMID 37675121, 2023). "In contrast, there was only weak correlation between PD-L1 IHC in TILs and CD274 expression in whole-tumor samples across the cohort (n = 222 with available TIL IHC data, (P = 0.008, ⍴ = 0.18)." (PMID 35881197, 2023). "A key mechanism pathway leading to tumor immune evasion is the interaction of the well-known immune checkpoints CD279 (programmed cell death protein 1, (PD-1), expressed on immune cells) and CD274 (programmed death ligand 1, (PD-L1), expressed on tumor cells)." (PMID 36834728, 2023). "One of the major immune checkpoints is PD-L1, encoded by the CD274 gene, which can inhibit T cell priming against tumor antigens and induce tumor growth and progression in multiple tumors." (PMID 37046851, 2023). "PD-L1 IHC and CD274 expression in tumor cells were highly correlated (n = 295, P < 2.2e-16, ⍴ = 0.74)." (PMID 35881197, 2023). "PD-L1 (also known as B7-H1 or CD274) is expressed on a sizeable fraction of tumor types and is one of the most critical." (PMID 36827173, 2023). "The immunosuppressive role of IL‐1β was due to its upregulation of immune‐suppressing genes in different tumor cells, with CD274 being the most consistently upregulated gene." (PMID 37009412, 2023).
tumor (continued). "Patients with CD274 low expression (n = 426) in their tumor harbored a significantly shorter overall survival than patients with CD274 high expression (n = 656) in their tumor (log rank test p-value = 0.022)." (PMID 38201582, 2023). "One study performed a gain-of-function screen for tumor resistance against T cell cytotoxicity and identified CD274, MCL1, JUNB, and B3GNT2 which enable melanoma cells to evade CTL killing." (PMID 37732732, 2023). "CD274 (PD-L1), expressed on the surface of tumor cells, is a ligand of PD-1, which can transmit inhibitory signals and mediate the immune escape effect of tumor cells." (PMID 37280630, 2023). "These RANO-treated tumours displayed increased expression of antigen presentation genes, as well as Ifnb1, Ifng and Cd274, indicating that RANO is effective in inducing an immunogenic phenotype in vivo." (PMID 37563469, 2023). "Because immune checkpoint genes such as CD274 (PDL1) and CTLA4 can cause T-cell dysfunction, preventing cytotoxic T cells from targeting tumor cells and promoting tumor progression." (PMID 38071230, 2023). "CD274, also known as programmed cell death ligand 1 (PD-L1), is overexpressed in tumor cells to perform immune escape function by binding to PD-1 on the surface of CD8+ T cell." (PMID 36212130, 2022). "Secondly, checkpoint PD-1/PD-L1 (CD274) has been reported as a pivotal mediator of immunosuppression in the tumor immune microenvironment." (PMID 36439512, 2022). "SIGLEC15, PDCD1LG2 (PD-L2), TIGIT, PDCD1 (PD-1), HAVCR2 (TIM3), CTLA4, LAG3, and CD274 (PD-L1) are transcripts related to immunological checkpoints that have a function in tumor immune evasion." (PMID 36042287, 2022). "It showed that all inhibitory checkpoint molecules except for CD274 are significantly upregulated in the HCC tumor group." (PMID 35444645, 2022). "The interaction of PDCD1/CD274 (PD‐L1) on the cell surface promotes T cell tolerance, minimizes autoimmune‐mediated inflammation, but also mediates the immune escape of tumour cells." (PMID 35802807, 2022). "IRF1 is a well‐known transcription factor to regulate tumour cell PD‐L1 expression by binding to CD274 promoter, and BRD4 is another key mediator of both tumour cell constitutive and IFN‐γ‐stimulated CD274 transcription." (PMID 35083874, 2022). "Diversification was characterized by M2.CXCL10 macrophage enrichment in HRD-Dup and depletion in FBI, with FBI tumours also exhibiting fewer PD-L1 (CD274)-positive macrophages." (PMID 36517593, 2022). "Antibodies against the immune checkpoints CTLA-4 or PDCD1/CD274 (also known as PD-1/PD-L1) can reactivate the T-cell anti-tumor activity that is abrogated in many cancers." (PMID 35234863, 2022). "In solid tumors, the interaction between CD274, present on the tumor front, and CD279 prevents T-cells clonal expansion, evading the suppressive innate immune response." (PMID 36013315, 2022). "For instance, BRD4 is a BET family protein that affects tumor immunity by regulating transcription of the CD274 (PD-L1) gene in certain cancer cells." (PMID 35517410, 2022). "PD-L1, also known as CD274 or B7-H1, is a transmembrane glycoprotein expressed by tumor cells, macrophages and T cells." (PMID 35311117, 2022). "To further explore the role of G6PD in the tumour immune microenvironment, we also analysed the association between G6PD and immune checkpoint molecules (PDCD1, CD274 and CTLA4)." (PMID 35712981, 2022). "Cd274 and Zbtb32 negatively regulate immunity, and S100a4, Rap1gap, Armc3, and Prkar2b promote tumor metastasis, This was consistent with the emergence of immunosuppression in the later stages of E. granulosus infection and with the hydatid cyst metastasis." (PMID 36569953, 2022). "Conversely, other immunoregulatory genes, such as CD274 (coding for PD-L1), IL1R2 (decoy IL1 receptor), and CD163 (marker of M2 and tumor-associated macrophages) were found to be upregulated at the time of diagnosis." (PMID 36230815, 2022).